MYC (MYC proto-oncogene, bHLH transcription factor)
Diseases named in the same sentence as MYC in open-access papers (continued):
Sharing a sentence is not in itself a finding about the gene and the disease.
lymphoma (continued). "The inverse correlation of the Myc-index and the BCR.1 index suggests that in lymphomas with a high MYC expression corresponding BCR.1 genes are highly expressed (low BCR.1 index, high gene expression) and thus most likely indicates an absence of a strong antigen stimulation." (PMID 27166259, 2016). "MYC oncogene rearrangements impart an unfavorable prognosis on lymphomas." (PMID 27580852, 2016). "Consistent with our observation in U2OS cells, expression of both clock genes correlated inversely with MYC levels in human lymphoma (Pearson coefficient −0.61 and −0.37 for BMAL1 and CLOCK, respectively; n=102), whereas MYC-activated genes such as NCL and NCLN showed a positive correlation." (PMID 27339797, 2016). "In a MYC-driven model of lymphoma, 4EBP1 is hyperphosphorylated in an mTOR-dependent manner." (PMID 25537515, 2015). "Hence, in established lymphomas, miR-17-19b fine-tunes c-MYC activity through a tight control of its function and expression, ultimately ensuring cancer cell homeostasis." (PMID 26555894, 2015). "Indeed, a modest increase in MYC levels was sufficient to fully restore the fitness of lymphoma cells expressing transgenic miR-17-19b." (PMID 26555894, 2015). "Yet, in spite of the wealth of information collected on the activity of miR-17-19b during lymphoma onset, the role of the cluster in established MYC-dependent tumours remains largely unknown." (PMID 26555894, 2015). "The synergism between c-MYC and miR-17-19b plays an important role in lymphoma initiation." (PMID 26555894, 2015). "Moreover, the deletion of miR-17-92 in established MYC-driven lymphoma cell lines decreased the capability to growth in tissue culture and immunodeficient hosts, in keeping with the concept that miR-17-92 levels influences proliferation of these cells." (PMID 26305986, 2015). "MYC rearranged DLBCL may arise de novo or may represent at high-grade transformation of a low-grade lymphoma, in which case most commonly disease was follicular lymphoma (FL)." (PMID 26416427, 2015). "Taken together, these observations provide a rational for targeting PIM1 and PIM2 in c-MYC expressing aggressive lymphomas including ABC-DLBCL and BL, in which PIM kinase inhibition might reduce c-MYC-mediated cell proliferation." (PMID 26643319, 2015). "Burkitt lymphoma and other lymphomas that carry MYC translocations are highly proliferative tumors." (PMID 26416427, 2015). "MYC rearrangements have subsequently been found in other subtypes of aggressive lymphomas." (PMID 24870942, 2014). "Moreover, declining levels of ligand transcripts in Runx2/MYC thymus offers a rationale for the accelerated dissemination of lymphoma cells towards highly expressing peripheral lymphoid tissues." (PMID 24586197, 2014). "In addition, conditional activation of K-ras and c-MYC oncogenes in mice shortened the lymphoma latency compared to inactivation of either oncogene alone, demonstrating that MYC and RAS can collaborate to promote lymphomagenesis." (PMID 24937171, 2014). "Thus, we analyzed 46 B-NHL samples with known karyotypes spotted on TMAs for hallmark lymphoma-associated translocations of the IGH-, BCL2, BCL6- and MYC-genes." (PMID 24733537, 2014). "MYC is essential for cell proliferation and is a proto-oncogene frequently upregulated in lymphoma." (PMID 24586676, 2014).
lymphoma (continued). "The frequency of MYC mutation, amplification and translocation increase in a subset of CLL with aggressive disease (30% of the cases) and in the CLL transformation to high grade lymphoma known as Richter syndrome." (PMID 25051361, 2014). "For example, a lymphoma specimen that coexpresses high levels of MYC and BCL2 proteins may respond better to a combination regimen that targets both proteins." (PMID 24870942, 2014). "In GSTT1-knock-down zebrafish, although may not initially be lethal, genomic lesions in lymphocytes could be modulated by PAH that promote lymphocyte proliferation and MYC upregulation, which could eventually link to malignant transformation of lymphoma." (PMID 24586676, 2014). "Interestingly, recent findings suggest that blockage of c-MYC downstream effectors affected glycolysis and glutathione biosynthesis in MYC-driven mouse lymphoma models." (PMID 24980829, 2014). "As another example, lymphoma, a top-related disease to adenocarcinoma of lung by onGrid, was observed to have the same effect with adenocarcinoma of lung in the combined inactivation of oncogenes MYC and K-ras in a study using mouse models." (PMID 25600290, 2014). "In the relapsed and refractory setting, salvage chemotherapy and auto stem-cell transplantation outcomes are extremely poor for patients with MYC+ disease (CORAL study: Collaborate Trial in Relapsed Aggressive Lymphoma), where 75% patients had FISH evidence of DHL." (PMID 24893165, 2014). "This was also proven by us in PAH-treated lymphoma cells, where MYC might ensure proliferative advantage through selectively activating CHK1." (PMID 24586676, 2014). "MYC rearrangements have been reported in 10–15% of systemic DLBCL, and they have been associated with a poor prognosis either alone or in combination with BCL2 rearrangements (“double-hit” lymphomas)." (PMID 25479599, 2014). "For the hsa-miR-132-3p/hsa-miR-212 cluster, 26 sets correlated significantly with both miRNAs, of which 12 were related with B cell progenitor/lymphoma or modulated upon MYC activation, further suggesting the relevance in MYC amplified cellular activation, proliferation and oncogenesis." (PMID 23560086, 2013). "Another reason for the failure of whole c-MYC protein or low efficacy of the large peptide vaccine to protect mice against lymphoma challenge might be the presence of regulatory T-cells." (PMID 24130880, 2013). "In view of the fact that CYCLON acts as an independent tumour growth driver in MYC-driven lymphoma, and that MYC and CYCLON overexpression controls a JQ1-sensitive Rituximab resistance pathway, we next wished to investigate the possible links between CYCLON activity and BET bromodomain inhibition." (PMID 23828858, 2013). "Furthermore, CYCLON was identified to be an autonomous tumour growth driver that cooperates with MYC to drive aggressive lymphoma growth in vivo thus further rationalizing the value of therapeutically targeting this factor in lymphoid malignancies." (PMID 23828858, 2013). "To see whether a similar mechanism holds true for B cell lymphomas, we transplanted antigen expressing λ-hu-MYC lymphoma cells into T cell-depleted bm1 mice and treated the mice with OT-I T cells." (PMID 22479645, 2012). "Finally, picolog was highly potent at 100 micrograms/kg and well tolerated at doses ranging from 100 micrograms/kg to 1 milligram/kg in vivo for the treatment of our aggressive model of MYC-induced lymphoma." (PMID 22308267, 2012). "Importantly, lymphomas with a typical DLBCL morphology that have a MYC breakpoint are excluded from the category of BCLu-DLBCL/BL." (PMID 22548066, 2012). "Besides OVA, human c-MYC (in the double transgenic model) or human c-MYC plus GFP (in the retrovirally transduced lymphoma model) are expressed as foreign antigens whose potential as tumor rejection antigens have not been explored." (PMID 22479645, 2012).
lymphoma (continued). "Thus, to study the potential efficacy of picolog in an in vivo model with direct clinical implications, we selected the conditional transgenic model of a rapidly progressive lymphoma arising from MYC overexpression in the lymphoid compartment." (PMID 22308267, 2012). "Although the nature of stroma cells in our λ-hu-MYC lymphoma model requires further investigation, our data support an auxiliary role of stroma cells in a murine high-grade NHL model and stress the importance of targeting the stroma during immunotherapy for non-solid tumors as well." (PMID 22479645, 2012). "Chromosomal translocations are common in leukemias and lymphomas, and the best known examples are reciprocal translocations in BL involving the MYC locus at FRA8C to any of the three immunoglobulin genes on chromosome 2, 14, or 22, resulting in MYC gene deregulation." (PMID 22580498, 2012). "Similarly, in Human acute T-cell lymphoblastic leukemias and lymphomas (T-ALL) gain-of-function mutants of Notch1 ensure robust transcriptional activation of MYC." (PMID 22373487, 2012). "On the other hand, the down-regulation of MYC in U87-MG cells, fits the result of a recently published paper where the suppression of MYC oncogene triggers cellular senescence, in diverse tumor types including hepatocellular carcinoma, osteosarcoma and lymphoma." (PMID 18694480, 2008). "Subsequent to initial studies demonstrating that forced expression of MYC in lymphoid tissues resulted in lymphoid hyperplasia and lymphomas, virtually all other studies of constitutive or inducible MYC in tissues from skin to liver resulted in neoplastic transformation of the targeted tissue." (PMID 18628958, 2008). "To examine how the MYC and K-rasG12D oncogenes cooperate for the initiation and maintenance of tumorigenesis, we generated double conditional transgenic tumor models of lung adenocarcinoma and lymphoma." (PMID 18461184, 2008). "However, the combined inactivation of both K-rasG12D and MYC was capable of inducing complete regression in both lung tumors and lymphomas." (PMID 18461184, 2008). "Next, we examined the consequences of MYC and/or K-rasG12D inactivation in lymphoma." (PMID 18461184, 2008). "Specifically, we have demonstrated that the K-Ras pathway and its down-stream effector Stat3 are correlated with the ability of K-rasG12D or MYC to initiate lung tumorigenesis and that down regulation of the K-Ras/Stat pathway is strongly correlated with lung tumor and lymphoma regression." (PMID 18461184, 2008). "Notably, in lymphomas, γH2AX and MYC scores were 10X more variable than in hemangiosarcomas." (PMID 40970130, 2025). "This indicated that BCL-2 and c-MYC may synergize to transform B lymphoid cells, but he held a lingering worry that if the Eμ-Myc transgenic mice that provided the bone marrow had a pre-clinical lymphoma, the results might have been skewed." (PMID 40204952, 2025). "However, the NYC oncogene MYC has been proven to inhibit tumor growth in lymphoma animal models." (PMID 39281673, 2024). "For instance, since MYC overexpressing lymphomas escape rituximab-mediated cytotoxicity by downregulating CD20, patients may benefit from agents that upregulate CD20, such as the histone deacetylase (HDAC) inhibitor valproate, the chemotherapeutic gemcitabine or PIM kinase inhibitors." (PMID 39596160, 2024). "However, lymphoma cells could upregulate MCL-1 and MYC upon venetoclax treatment, which might cause resistance to venetoclax." (PMID 38918775, 2024).
lymphoma (continued). "Our cohort includes 3 patients with variant 3’MYC loss and 1 patient with 5’MYC poly-signaling; all the patients in our cohort with variant MYC signaling had concurrent BCL2 rearrangements, raising the possibility of whether these were “double-hit” lymphoma." (PMID 38903717, 2024). "The lymphoma-intrinsic MYC-mediated suppression of T-cell activation may occur via the increased secretion of immunosuppressive cytokines, inhibition of inflammatory signaling or modulation of accessory molecules involved in immune synapses and the immunosuppressive tumor microenvironment." (PMID 39596160, 2024). "However, when restricting the analysis to lymphoma cell lines only, we observed a significant correlation between MYC and HSP90AB1 dependencies that was among the strongest MYC correlations on a transcriptome-wide level (Pearson correlation, Rho = 0.44, p = 0.0091)." (PMID 38326887, 2024). "Indeed, when separating lymphomas into MYC-dependent and -independent cell lines, we observed that HSP90AB1 dependency scores were significantly lower in MYC-dependent compared to MYC-independent cell lines, indicating a potential relationship between HSP90AB1 and MYC (t-test, p = 0.021)." (PMID 38326887, 2024). "Since EBF1, PAX5, and MYC are essential for B cell development, their ectopic expression or mutants may lead to abnormal B cell development and hematologic neoplasms, such as B-lymphoid leukemia and lymphoma." (PMID 38318177, 2024). "Furthermore, MYC-driven lymphomas are highly dependent on MCL1 for survival." (PMID 37766215, 2023). "More intensive therapy may improve survival for MYC‐rearranged lymphoma." (PMID 36695162, 2023). "Hence, complex I inhibition and high‐dose ascorbate might improve the outcome of patients affected by high‐grade lymphomas and potentially other MYC‐driven cancers." (PMID 37158102, 2023). "Moreover, MCL-1 over-expression greatly accelerates the development of c-MYC driven lymphoma." (PMID 36342579, 2023). "Therefore, to inhibit the PRMT5/MSI2/c-MYC/BCL-2 axis we proposed two drug combination strategies; the first one consists of targeting PRMT5 in combination with a MSI2 inhibitor, which results in loss of c-MYC and BCL-2 translation cell-cycle regulators in lymphoma cells." (PMID 36167829, 2022). "Indeed, CHK1 inhibitors proved effective in killing murine MYC‐driven lymphoma." (PMID 36214609, 2022). "Therefore, we propose that the upregulation of both hsa-miR-20a-5p and the corresponding lncRNA pair SNHG16 is due to the preponderant action of the deregulated MYC in lymphomas, which acts as a transcription factor of both genes in order to promote lymphoma cells’ proliferation and survival." (PMID 35740344, 2022). "Besides double-hit (DH) or triple-hit (TH) lymphomas, referring to translocations involving the MYC and BCL2 and/or BCL6 genes detected via FISH, the double-expressor (DE, assessed by IHC) lymphoma phenotype refers to strongly detectable protein expression of the MYC and BCL2 gene products." (PMID 35326604, 2022). "Additionally, bromodomain inhibitors (BET) have proven efficacy in MYC amplified lymphoma." (PMID 34638300, 2021).
lymphoma (continued). "The survival disadvantage of EZB/C3 DLBCLs may be at least partially explained by the fact that the mutational characteristics of double hit (DHIT) lymphomas, an aggressive subtype of DLBCL characterized by MYC and BCL2 translocation, are enriched in this category." (PMID 35071240, 2021). "All lymphomas showed reduction in methylation relative to thymocytes with the highest percentage of hypomethylated DMCs (≥30% change in methylation as analyzed by Metilene based on average of two samples) present in MYC;Dnmt3bΔ/Δ lymphomas (21.1%) and the lowest in Dnmt3b+/− PTCL (9.6%)." (PMID 33450231, 2021). "In many cases, such rearrangements lead to lymphoma in the absence of mutations in MYC." (PMID 34885204, 2021). "It has been shown that upregulation of MYC leads to increased surface expression of transferrin receptor (TfR), hence 89Zr-transferrin was developed as a potential probe for MYC status and tumor burden in several cancer models, such as prostate cancer and lymphoma." (PMID 33986665, 2021). "Hence, eIF4A1 inhibition could be a new and effective treatment for aggressive and MYC+/BCL2+ lymphomas." (PMID 33562682, 2021). "Furthermore, karonudib was also potent in lymphoma cells regardless of the mutational or translocation status of MYC." (PMID 33737576, 2021). "However, 11q-gain/loss is not specific to this subgroup of lymphomas and can be seen in MYC-positive BL and MYC-positive (HGBL-NOS)." (PMID 34283060, 2021). "However, more recent work has shown that it may participate in other processes, such as nuclear factor κB (NF-κB) activation, development, and expansion of MYC-driven lymphomas and innate B cell development (36, 37, 49, –, 52)." (PMID 32041786, 2020). "Although MYC rearrangements partially explain the high MYC expression in all BLs and non-Burkitt high-grade BCLs, there is no consensus regarding the causes of high MYC levels in lymphomas without MYC rearrangement." (PMID 33298911, 2020). "Most types of lymphoma present high levels of MYC expression that are not always correlated with a mutated MYC gene, opening the door to speculation that, as in leukemia, multiple pathways may act to facilitate its dysregulation." (PMID 32102485, 2020). "Thus, high MYC expression may be mainly caused by a decreased interaction of UBE3B and MYC, which is induced by elevated TRIB3 expression in lymphoma cells." (PMID 33298911, 2020). "In the setting of deregulated MYC, samples with ID3 mutations show a higher level of expression of known MYC target genes, and give rise to increased G1-to-S-phase cell-cycle progression in BL, suggesting a role for ID3 as a tumor suppressor in this type of lymphoma." (PMID 32102485, 2020). "FoxO inhibition in dnFoxO-expressing MYC-driven lymphomas promotes cell proliferation, while that in ARF-deficient MYC-driven lymphomas does not affect tumorigenicity, suggesting that FoxO inhibits MYC-derived lymphomagenesis by binding to the ARF promoter and inducing ARF expression." (PMID 32759846, 2020). "Notably, TRIB3 knockdown reduced MYC expression in most lymphoma lines and in some leukemia lines." (PMID 33298911, 2020). "Among the participants given R-CHOP (including the non-randomised group), MYC rearrangement, double-hit lymphoma, and dual high MYC and BCL-2 mRNA expression were significantly associated with inferior progression-free survival after controlling for IPI (data not shown)." (PMID 30948276, 2019). "Similarly, lymphoma cell lines that have a MYC translocation and a high level of Myc protein are sensitive to Omomyc, with a 50% effective concentration (EC50) range of 0.4 to 1.1 μM, whereas lymphoma cell lines with low MYC RNA and low Myc protein levels are insensitive to Omomyc." (PMID 31501275, 2019).